HORMAD1 (HORMA domain containing 1)
Description:
Plays a key role in meiotic progression. Regulates 3 different functions during meiosis: ensures that sufficient numbers of processed DNA double-strand breaks (DSBs) are available for successful homology search by increasing the steady-state numbers of single-stranded DSB ends. Promotes synaptonemal-complex formation independently of its role in homology search. Plays a key role in the male mid-pachytene checkpoint and the female meiotic prophase checkpoint: required for efficient build-up of ATR activity on unsynapsed chromosome regions, a process believed to form the basis of meiotic silencing of unsynapsed chromatin (MSUC) and meiotic prophase quality control in both sexes.
Synonyms: CT46; NOHMA; DKFZP434A1315
Tractability: No criterion of Open Targets' tractability assessment is met for any kind of drug.
Gene: Protein-coding gene on chromosome 1 (150,698,060 to 150,720,895, reverse strand). Ensembl gene ENSG00000143452.
Subcellular location: Nucleus; Chromosome
Subcellular location (Human Protein Atlas): Nucleoplasm; Nucleoli
Gene Ontology:
Molecular function: protein binding
Biological process: blastocyst development; meiotic cell cycle; meiotic DNA double-strand break formation; meiotic recombination checkpoint signaling; meiotic sister chromatid cohesion; oogenesis; regulation of homologous chromosome segregation; spermatogenesis; synaptonemal complex assembly
Cellular component: nucleus; chromosome; synaptonemal complex; condensed nuclear chromosome
Genetic constraint (gnomAD): Loss-of-function variants: 2 observed, 8.42 expected, observed/expected ratio (o/e) 0.24, 90% interval 0.096 to 0.75. That is too few expected variants to judge how well the gene tolerates losing a copy. Missense variants: 103 observed, 119.98 expected, observed/expected ratio (o/e) 0.86, 90% interval 0.73 to 1.01. Synonymous variants: 31 observed, 37.5 expected, observed/expected ratio (o/e) 0.83, 90% interval 0.62 to 1.12.
Homologues: Orthologues: macaque HORMAD1 (99% identical), chimpanzee HORMAD1 (99% identical), dog HORMAD1 (92% identical), pig HORMAD1 (91% identical), rabbit HORMAD1 (84% identical), guinea pig HORMAD1 (83% identical), rat Hormad1 (78% identical), mouse Hormad1 (78% identical), tropical clawed frog hormad1 (57% identical), zebrafish hormad1 (43% identical), Caenorhabditis elegans him-3 (18% identical), Caenorhabditis elegans htp-1 (17% identical), and 1 more. Paralogues in human: HORMAD2 (39% identical).
Diseases named in the same sentence as HORMAD1 in open-access papers:
HORMAD1 is named in the same sentence as 26 diseases in open-access papers, as found by Europe PMC text mining. Sharing a sentence is not in itself a finding about the gene and the disease. The quoted sentences say what the papers report.
breast carcinoma (14 papers, 2016 to 2025). "Overall, HORMAD1 expression is upregulated in cancer, including gastric cancer, lung cancer, breast cancer and ovarian cancer, and has been associated with increased genomic instability and worse overall survival." (PMID 38596293, 2024). "Among breast cancer subtypes, HORMAD1 overexpression best associates with the BLBC subtype (83.6%), a stronger association than the TNBC subtype (69.6%) described previously." (PMID 30046392, 2018). "We investigated the promoter methylation status of BRCA1 and HORMAD1 to explore if aberrant methylation of these candidate drivers of genomic instability in basal-like breast cancer was associated with subsets of ET7 tumors." (PMID 26923702, 2016). "Therefore, it is necessary to reevaluate the premise that the genomic instability associated with HORMAD1 expression in breast cancer (Watkins) and lung adenocarcinoma (this report) is necessarily caused by HR defects." (PMID 30333500, 2018). "For example, in breast cancer, the CTAs CXorf61, HORMAD1, ACTL8 and PRAME are specifically enriched in basal subtypes, while the expression of PLAC1 and POTEC is more frequently observed in non-basal subtypes." (PMID 38596293, 2024). "Landemaine and colleagues predicted previously that HORMAD1 and other genes correlate with lung metastasis in breast cancer." (PMID 35347116, 2022). "In these lines, expression levels of HA tagged HORMAD1 were comparable to those seen in the HORMAD1 positive breast cancer cell line MDA-MB-436." (PMID 35768547, 2022). "HORMAD1 is aberrantly expressed in multiple cancers, such as ovarian cancer, breast cancer, and lung cancer." (PMID 35347116, 2022). "HORMAD1 is a specific germ cell protein that plays an important role in homologous chromosome recombination, and is reactivated in breast cancer, showing abnormally high expression." (PMID 34502549, 2021). "It was recently reported that HORMAD1 is overexpressed in triple-negative breast cancer (TNBC), and HORMAD1 expression sensitizes breast cancer cells to homologous repair (HR)-defect targeting agents by contributing to homologous recombination deficiency." (PMID 30046392, 2018). "In this study, we show that HORMAD1 is preferentially overexpressed in the BLBC subtype of breast cancer based on analysis of the TCGA and Metabric datasets." (PMID 30046392, 2018). "The 1q21 amplicon also contains HORMAD1, a gene that has been shown to drive chromosomal instability in breast cancer." (PMID 29456550, 2018). "As a parallel study, our group independently discovered that HORMAD1 is overexpressed in a subset of breast cancers, most of which belong to the basal-like subtype." (PMID 30046392, 2018). "Those workers attributed the increased CNA of HORMAD1-overexpressing breast cancer cells to reduced HR, and compensatory increases in alternative error-prone DSB repair activities." (PMID 30333500, 2018). "HORMAD1 expression levels across breast cancer tissues were determined by qPCR, and HORMAD1 expression levels across breast cancer cell lines was determined by Nanostring assay." (PMID 30046392, 2018). "A number of candidate effectors of SOX11 signalling in DCIS were identified, including ALDH1A1 and HORMAD1, which have established links to breast cancer." (PMID 28707729, 2017). "In a cohort of 526 breast cancer patients, HORMAD1 was overexpressed in 71% of TNBC." (PMID 36852691, 2023). "We confirmed doxycycline-induced expression of HORMAD1 in these clones and also showed that the HORMAD1 expression level achieved in these models is comparable to that found in the endogenous HORMAD1 expressing breast cancer line MDA-MB-436." (PMID 35768547, 2022). "Moreover, HORMAD1 has been shown to enhance tumor growth in xenograft models of basal-like breast cancer." (PMID 35347116, 2022).
breast carcinoma (continued). "To assess HORMAD1 expression in breast cancer subtypes, we analyzed RNAseq data for breast cancer from The Cancer Genome Atlas (TCGA) and associated HORMAD1 expression with receptor status, clinicopathological subtypes, and Prediction Analysis of Microarray 50 (PAM50) groups." (PMID 30046392, 2018). "For example, tissue-specific expression of putative HR pathway regulators targeted by HORMAD1 might explain why HORMAD1 stimulates HR in lung adenocarcinomas and basal breast cancer cells and but inhibits HR in TNBC." (PMID 30333500, 2018). "Similar to the brc-1 ortholog BRCA1, HORMAD1, SETD1A, KMT2C, and KM2D/MML4 have all been linked to breast cancer, suggesting that these genetic interactions may be conserved in human cells." (PMID 28506208, 2017). "However, directed analyses showed that BRCA1 and HORMAD1 are clear candidates for driver genes directly regulated by aberrant methylation in some basal-like breast cancers." (PMID 26923702, 2016). "Studies have shown that under the conditions of oxidative stress induced by related chemotherapy drugs, HORMAD1 may regulate the expression of enzymes in breast cancer cells to enhance the ability to resist apoptosis, which may be the main factor in inducing chemotherapy resistance." (PMID 34502549, 2021). "However, biological functions as well as molecular mechanisms of these genes in breast cancer should be further investigated, as only 8 and 2 papers were available when PubMed was searched with keywords “breast cancer + HORMAD1” or “breast cancer + ART3,” respectively." (PMID 34108519, 2021). "In breast cancer cell lines as well, 70% of basal-like cell lines from CCLE were positive for HORMAD1 or CT83 and 35% for both." (PMID 38467851, 2024). "In total, these results illuminate the potential for HORMAD1 and CT83 use as biomarkers for basal-like breast cancers by showing both their specificity for the subtype as well as the functional consequences of their co-activation." (PMID 38467851, 2024). "To verify epigenetic activation of HORMAD1 overexpression, we investigated the methylation status of the HORMAD1 promoter region by Pyrosequencing in 45 TNBC tumors and 14 breast cancer cell lines." (PMID 30046392, 2018). "We treated the MCF10A benign basal epithelial cell line and the HCC1806 basal breast cancer cell line, neither of which overexpress HORMAD1, with 5-aza." (PMID 30046392, 2018).
triple-negative breast carcinoma (10 papers, 2018 to 2025). An invasive breast carcinoma which is negative for expression of estrogen receptor (ER), progesterone receptor (PR), and human epidermal growth factor receptor 2 (HER2). "Association between HORMAD1 mRNA expression and histopathological and clinical characteristics of 186 triple negative breast cancer patients." (PMID 36852691, 2023). "HORMAD1 expression is usually restricted to germline cells, but it becomes mis-expressed in epithelial cells in ~60% of triple-negative breast cancers (TNBCs), where it is associated with elevated genomic instability." (PMID 35768547, 2022). "Previous studies have shown that triple-negative breast cancers with aberrant HORMAD1 expression is associated with genomic instability." (PMID 32647118, 2020). "HORMAD1 has been identified as a driver of genome instability in triple-negative breast cancers by suppressing RAD51-dependent HR, leading to increased reliance on nonhomologous end joining pathways." (PMID 40918650, 2025). "To further corroborate this apparent synergistic effect of HORMAD1 and CT83 expression, we performed loss-of-function experiments in a triple-negative breast cancer line that endogenously expresses both genes, MDA-MB-436." (PMID 38467851, 2024). "The role of HORMAD1 in DNA repair and the chemotherapeutic response has been reported in various cancers, including ovarian cancer, basal-like and triple-negative breast cancer, and lung cancer." (PMID 35347116, 2022). "Notably, the role of HORMAD1 and thus meiomitosis is not restricted to SCCs, since other cancers with high mutational burdens, including triple negative breast cancer (TNBC) and lung adenocarcinoma, also express high levels of HORMAD1." (PMID 37371097, 2023). "Using the histological classification of breast tumors, we found the same result: HORMAD1 and CT83 are the two best predictors of triple-negative breast cancers within C/T genes." (PMID 38467851, 2024). "To verify the differential HORMAD1 expression in TNBC tissues compared to ER-positive tumors, we performed reverse transcription PCR (RT-PCR) using two primer sets specific for HORMAD1 in 14 ER positive and 46 triple-negative breast cancer tissues." (PMID 30046392, 2018). "In the absence of treatment, we validated by RT-qPCR that these cell lines do not express HORMAD1 and CT83, in contrast to the triple-negative breast cancer line MDA-MB436." (PMID 38467851, 2024).
lung adenocarcinoma (8 papers, 2018 to 2025). A carcinoma that arises from the lung and is characterized by the presence of malignant glandular epithelial cells. "In lung adenocarcinoma tumors, high expression of HORMAD1 correlates with elevated mutational burden and reduced survival compared to tumors with low expression of HORMAD1." (PMID 37371097, 2023). "Kaplan–Meier analysis revealed that high HORMAD1 expression level was associated with poor prognosis of the patients in the lung adenocarcinoma microarray." (PMID 35347116, 2022). "In lung adenocarcinoma cells with aberrant HORMAD1 expression, HORMAD1 depletion causes HR deficiency and increased sensitivity to ionizing radiation or PARPi8,9." (PMID 32647118, 2020). "Owing to the new role we defined for HORMAD1 in promoting HR, it was of interest to determine whether HORMAD1 expression was associated with particular oncogenic drivers and tumorigenic events in lung adenocarcinoma." (PMID 30333500, 2018). "Conversely, HORMAD1, which are ectopically expressed in cancers such as lung adenocarcinoma and squamous cell carcinoma, promotes genomic instability." (PMID 40918650, 2025). "Here, we show that HORMAD1 is upregulated in lung adenocarcinoma tissues compared with adjacent normal tissues and that aberrant HORMAD1 expression predicts poor prognosis." (PMID 35347116, 2022). "HORMAD1 was significantly upregulated in pan-lung cancer, lung adenocarcinoma, and lung squamous cell carcinoma tissues compared to the paired noncancerous tissues." (PMID 35347116, 2022). "In contrast, two distinct studies demonstrated that HORMAD1 promotes HR in models of lung adenocarcinomas, providing a selective survival advantage for cancer cells." (PMID 35251135, 2022). "Fully consistent with Watkins and colleagues, our bioinformatic analyses of lung adenocarcinoma (TCGA) show that HORMAD1 expression is well correlated with AiCNA." (PMID 30333500, 2018). "HORMAD1-depletion in another lung adenocarcinoma cell line (A549) also led to attenuation of HR activity as measured by DR-GFP reporter assay." (PMID 30333500, 2018). "Bioinformatic analysis of TCGA data show that similar to known HR pathway genes HORMAD1 is overexpressed in lung adenocarcinomas." (PMID 30333500, 2018). "HORMAD1 IRIF were also readily detectable in other cancer cell lines including A549 lung adenocarcinoma, and U2OS osteosarcoma." (PMID 30333500, 2018). "In studies with isogenic cells we observe HORMAD1-dependent HR pathway activation in several cell lines including lung adenocarcinoma and TNBC." (PMID 30333500, 2018). "Genomic alterations and gene expression events in HORMAD1 correlate with a diverse set of tumorigenic mechanisms in lung adenocarcinoma." (PMID 30333500, 2018). "To further validate the protein expression of HORMAD1 in lung cancer at different histologic stages, we detected HORMAD1 in a lung adenocarcinoma microarray containing 91 lung adenocarcinoma tissues and corresponding normal lung tissues by immunohistochemistry." (PMID 35347116, 2022). "Our study showed that HORMAD1 expression in lung cancer tissues is evidently increased compared to that in normal tissues and that increased HORMAD1 expression results in unfavorable prognostic outcomes in lung adenocarcinoma patients." (PMID 35347116, 2022). "To assess the clinical significance of HORMAD1 expression in lung cancer, we first analyzed the HORMAD1 expression level in pan-lung cancer, lung adenocarcinoma and lung squamous cell carcinoma using RNA sequencing (RNA-seq) data from The Cancer Genome Atlas (TCGA)." (PMID 35347116, 2022). "We tested a potential role of HORMAD1 in genome maintenance in lung adenocarcinoma cells." (PMID 30333500, 2018). "Downregulation of HORMAD1 in SCCs cancer cells sensitized them to etoposide treatment and may sensitize HORMAD1 dependent cells/tumors to other chemotherapy treatments, as demonstrated in studies involving breast and lung adenocarcinoma models." (PMID 37371097, 2023).
lung adenocarcinoma (continued). "Twelve types of cancers were in group I, including lung adenocarcinoma (LUAD) and breast invasive carcinoma (BRCA), in which HORMAD1 high expression has been confirmed by previous studies." (PMID 32647118, 2020). "Taken together, we identify HORMAD1-dependent DSB repair as a new mechanism of radioresistance and a probable determinant of mutability in lung adenocarcinoma." (PMID 30333500, 2018). "Expression of HORMAD1 in lung adenocarcinomas did not correlate with other expressed CT antigens that cooperate with HORMAD1 during meiotic recombination." (PMID 30333500, 2018). "This may explain why HORMAD1 inhibits HR in TNBC and stimulates HR in lung adenocarcinomas." (PMID 35251135, 2022). "Indeed, and consistently with previous reports on CT genes, the expression of the meiosis specific gene HORMAD1, the MAGE-A gene family, and the sperm specific cytochrome c oxidase COX6B2, we found that a high GC signature score correlates with poor prognosis in lung adenocarcinoma." (PMID 33348709, 2020).